PCDH11X (protocadherin 11 X-linked)
Description:
Potential calcium-dependent cell-adhesion protein.
Synonyms: PCDH-X; PCDH11; PCDHX; PPP1R119; PCDH-Y; PCDH11Y; PCDH22
Tractability: Antibody: UniProt places it where antibodies can reach, with high confidence; its Gene Ontology location is reachable by antibodies, with high confidence; UniProt predicts a signal peptide or a membrane-spanning region. PROTAC: its protein half-life has been measured.
Gene: Protein-coding gene on chromosome X (91,779,261 to 92,623,230, forward strand). Ensembl gene ENSG00000102290.
Subcellular location: Cell membrane
Subcellular location (Human Protein Atlas): Plasma membrane; Cytosol; Vesicles
Gene Ontology:
Molecular function: cell adhesion molecule binding; calcium ion binding
Biological process: cell adhesion; homophilic cell-cell adhesion
Cellular component: plasma membrane; membrane
Homologues: Orthologues: chimpanzee PCDH11X (99% identical), macaque PCDH11X (94% identical), mouse Pcdh11x (83% identical), rat Pcdh11x (82% identical), tropical clawed frog pcdh11x (60% identical), zebrafish pcdh11 (54% identical). Paralogues in human: PCDH11Y (91% identical), PCDH9 (50% identical), PCDH1 (33% identical), PCDH7 (33% identical), PCDH20 (23% identical), DCHS1 (18% identical), CDH23 (17% identical), DCHS2 (16% identical), CDHR2 (15% identical), CDH1 (14% identical), CDH2 (14% identical), CDHR1 (14% identical), and 21 more.
Diseases named in the same sentence as PCDH11X in open-access papers:
PCDH11X is named in the same sentence as 29 diseases in open-access papers, as found by Europe PMC text mining. Sharing a sentence is not in itself a finding about the gene and the disease. The quoted sentences say what the papers report.
breast carcinoma (3 papers, 2018 to 2021). "GJA1 encodes for connexin-43, a gap junction protein whose expression in breast cancer cells has been implicated in pulmonary metastasis, consistent with observed lung metastasis in both patients from which the ESR1-e6>YAP1 and ESR1-e6>PCDH11X fusions were identified." (PMID 30089255, 2018).
glioblastoma (3 papers, 2011 to 2020). The most malignant astrocytic tumor (WHO grade IV). "ECOP is co-amplified with EGFR in glioblastoma as well as other cancers, RUNX2 is expressed in glioblastoma cells, and PCDH11X is associated with late-onset Alzheimer's disease." (PMID 21510904, 2011). "Finally, we identified one gene, PCDH11X, for which the domain mutation patterns suggest an oncogenic role in lymphoma and leukemia but a tumor suppressive role in glioblastoma and medulloblastoma." (PMID 25794154, 2015). "Other examples include the two cadherin domain instances encoded by PCDH11X and PCDH11Y in glioblastoma." (PMID 25794154, 2015). "While there is little evidence concerning the role of PCDH11X in GBM, other protocadherin family members, such as PCDH-γ-A11, have been associated with astrocytomas, glioblastomas and glioma cell lines." (PMID 33237934, 2020).
adenoma (1 paper, 2024). A neoplasm arising from the epithelium. "Some MP-RNAs interacted with much more partners in adenoma and cancer tissues than in paracancer tissues, such as SLC16A14, POLA2, PCDH11X, TASP1, TSPY20P." (PMID 38773399, 2024).
atherosclerosis (1 paper, 2024). A disease characterized by the build-up of fatty material and calcium deposition in the arterial wall resulting in partial or complete occlusion of the arterial lumen. "The gene list included well-known atherosclerosis-associated genes Serpina3,42Cemip,43Thbs1,44Lum,45 and Spp146,47 but also novel genes without previous association to SMC function in atherosclerosis, such as Anxa4, Cd276, Itih4, Myof, Pcdh11x, Rab31, Serpinb6b, Slc35e4, Slc8a3, and Spink5." (PMID 38289873, 2024). "Moreover, we identified several novel genes not previously linked to SMCs in atherosclerosis, such as Anxa4, Cd276, inter-alpha-trypsin inhibitor-4 (Itih4), Myof, Pcdh11x, Rab31, Serpinb6b, Slc35e4, Slc8a3, and Spink5." (PMID 38289873, 2024).
breast tumors (1 paper, 2019). "These ESR1 fusions transcripts, ESR1-e6>YAP1 and ESR1-e6>PCDH11X, were identified in patients with metastatic ER+ breast tumors that were pan-endocrine therapy resistant." (PMID 31106278, 2019).
colorectal cancer (1 paper, 2024). A primary or metastatic malignant neoplasm that affects the colon or rectum. "X‐linked FLNA, TBX22, KIAA2022, IRS4, PCDH11X, GPR112, and F8 have been proposed as cancer‐related genes in colorectal cancer." (PMID 38827026, 2024). "The X‐linked cancer‐related genes FLNA, TBX22, KIAA2022, IRS4, PCDH11X, and GPR112 are connected to colorectal cancer." (PMID 38827026, 2024).
developmental delays (1 paper, 2024). "Duplication of Xq13.2-Xq21.31, the region containing YWHAZP8, along with other genes such as ATRX and PCDH11X, has been reported in a clinical case associated with X-inactivation, resulting in developmental delays and seizures in a boy with pubertal gynecomastia." (PMID 38674334, 2024).
epilepsy (1 paper, 2022). A brain disorder characterized by episodes of abnormally increased neuronal discharge resulting in transient episodes of sensory or motor neurological dysfunction, or psychic dysfunction. "With regard to implications for epilepsy, partial Pcdh11x duplication (as part of a broader Xq13-q21 duplication) was reported in one patient with recurrent seizures." (PMID 36117624, 2022).
language delay (1 paper, 2016). "For example, deletion of this gene was found in a patient with developmental dyslexia, and deletion of both PCDH11X and PCDH11Y was discovered in a child with non-syndromic language delay." (PMID 26759715, 2016).
cancer (6 papers, 2011 to 2024). A tumor composed of atypical neoplastic, often pleomorphic cells that invade other tissues. "Genes potentially associated with cell migration and cancer metastasis included CNTN5, FN1, Integrin Subunit Beta 6 (ITGB6), EPHB1, Unc-5 Netrin Receptor D (UNC5D), SDK1, RADIL, LRRC7, PCDH11X, and ADAMTS9." (PMID 39770638, 2024). "The cytodomain of PCDH11X has been shown to interact with β‐catenin, inducing the Wnt signaling pathway in cultured cancer cells." (PMID 34150649, 2021). "Additionally, ADNP2, PCDH11X, and MGST1 detected to be highly expressed in the transformed HGG model have been associated with EMT and treatment resistance in various cancer types." (PMID 39256867, 2024).
tumor (4 papers, 2015 to 2021). "Genes of interest involved in tumor progression or uterine fibroids, from previous studies, FGFR1, CCND1, PCDH11X, VDR, NDRG2 and INPP4B, are indicated in the volcano plot." (PMID 33807176, 2021). "Both in-frame fusions from advanced disease, ESR1-e6>YAP1 and ESR1-e6>PCDH11X, promoted estrogen-independent growth (−E2), but the primary tumor fusion event, ESR1-e6>NOP2, had no growth-promoting properties." (PMID 30089255, 2018).
PCDH11X also shares sentences with these, for which no sentence is quoted: Intellectual disability (3 papers); acute myeloid leukaemia (1); Alzheimer disease (1); astrocytomas (1); attention deficit-hyperactivity disorder (1); autism (1); Cognitive impairment (1); Gynecomastia (1); kidney cancer (1); leiomyoma (1); leukemia (1); lymphoma (1); medulloblastoma (1); neurodevelopmental disorder (1); psychiatric disorder (1); renal cell carcinoma (1); Wilms tumor (1); X-linked intellectual disability (1).